BAD (BCL2 associated agonist of cell death)
Diseases named in the same sentence as BAD in open-access papers (continued):
Sharing a sentence is not in itself a finding about the gene and the disease.
COVID-19 (4 papers, 2021 to 2023). A disease caused by infection with severe acute respiratory syndrome coronavirus 2. "The rete testis area presented degenerating germ cells, and BAD and BAX levels were augmented in nearly all COVID-19 patients." (PMID 36797789, 2023). "However, these apoptotic gene signatures were characterized by distinct DEGs expressed in the COVID-19(+) TV (BCLAF1, BCL2L1) and COVID-19(-) PU control groups (BAD, ACIN1, HIF1A)." (PMID 37026002, 2023). "The result suggested that the three NSAIDs' key mechanism against COVID-19 might be to inhibit inflammation of lung cells by inactivating the RAS signaling pathway, and blockers of MAPK8, MAPK10 and BAD might suppress cytokine storm." (PMID 33953223, 2021).
diabetes (4 papers, 2012 to 2016). "The BAD protein plays key role in both diabetes and AD pathology." (PMID 27151376, 2016). "Levels of pro-apoptotic proteins did not change in any IRS2−/− group regardless of diabetes: BAD (ND: 101%; D: 99% of WT values), truncated BID (t-BID)/BID (ND: 96%; D: 101% of WT values) and BIM (ND: 96%; D: 112% of WT values)." (PMID 27013528, 2016). "The discrepancy between the in vivo and in vitro models in relation to the effect of FOXO1 on PP2A could be the presence of excess lipids brought in by the FOXO1–CD36 pathway observed with diabetes, which turns on PP2A, thereby activating BAD stimulated apoptotic process." (PMID 26956801, 2016).
epilepsy (4 papers, 2015 to 2022). A brain disorder characterized by episodes of abnormally increased neuronal discharge resulting in transient episodes of sensory or motor neurological dysfunction, or psychic dysfunction. "A study found that in a rat model of epilepsy, seizures induced the dimerization of BAD with BcL-XL in the affected areas of the hippocampus." (PMID 36515436, 2022). "Mimicking the effect of BAD knockout on fuel preference using small molecules could be a valuable avenue for development of new epilepsy therapies." (PMID 29368690, 2018). "Common variants in KCNJ11 and BAD do not predict response to KDT for epilepsy." (PMID 26590798, 2015). "We sequenced KCNJ11 and BAD in individuals without previously-known glucose transporter type 1 deficiency syndrome or other metabolic disorders, who received KDT for epilepsy." (PMID 26590798, 2015).
glioblastoma (4 papers, 2014 to 2024). The most malignant astrocytic tumor (WHO grade IV). "In fact, the PIK3 inhibitor GDC-0941 has been shown to inhibit AKT phosphorylation of BAD, decrease MCL-1 expression, and inhibit the growth of glioblastoma cells in synergy with ABT-263." (PMID 31150457, 2019). "Naringin treatment of U251 glioblastoma cells and U87 glioblastoma cells restricts their growth by inhibiting the cyclin D1 pathway or FAK pathway and induces the death of cells by inhibiting the BAD pathway or FAK pathway." (PMID 37570594, 2023).
hepatocellular carcinoma (4 papers, 2015 to 2021). A malignant tumor that arises from hepatocytes.
chronic myeloid leukemia (3 papers, 2019 to 2020). "Similarly, others have shown that chronic myeloid leukemia (CML) cell line LAMA84-derived exosomes promote proliferation genes (BCL-xl, BCL-w, survivin) and downregulate pro-apoptotic genes such as BAD, BAX, and PUMA." (PMID 32932883, 2020). "In addition, exosomes from chronic myeloid leukemia and nasopharyngeal carcinoma tumors were used to promote proliferation of lymphocytes and other cells by increasing BCL-w, BCL-xl, and survivin, and a reduction of the pro-apoptotic molecules BAD, BAX and PUMA." (PMID 31426278, 2019).
liver cancer (3 papers, 2021 to 2025). An epithelial or non-epithelial malignant neoplasm that arises from the liver. "Animal experiments showed that SS-b2 significantly decreased the levels of MACC1, p-c-MET and p-Akt in tumour tissue transplanted with H22 liver cancer cells in mice, while it increased the expression of p-BAD." (PMID 39544485, 2024). "The findings demonstrated that SS-b2 exerts an anticarcinogenic effect on the HepG2 liver cancer cells, resulting in a reduction in the expression of the antiapoptotic protein Bcl-2 and an increase in the expression of the proapoptotic protein BAD." (PMID 39544485, 2024).
lung adenocarcinoma (3 papers, 2013 to 2021). A carcinoma that arises from the lung and is characterized by the presence of malignant glandular epithelial cells. "This is keeping with our previous report that overexpression of BAD suppressed cell proliferation in another lung adenocarcinoma cell line A549." (PMID 23725574, 2013). "Campesterol induced cell apoptosis through the mitochondrial pathway; it decreases the expression of BCL-2 and BCL-xL and increased the expression of BAX, BAD, BAK, and activating caspase 3 and caspase 9 in human lung adenocarcinoma (A549) cells." (PMID 33802602, 2021). "This is likely because SFN does not bind to proteins such as BAX or BAD, which regulate apoptosis or senescence in lung adenocarcinoma (data not shown, personal communication)." (PMID 26223682, 2015).
oral cancer (3 papers, 2015 to 2024). "Thyroxine is an enhancer of the proliferation and progression of oral cancer cells by the down-regulation of apoptotic factor BAD (B-cell lymphoma 2 (Bcl-2)-associated agonist of cell death) and up-regulation of PD-L1." (PMID 32486484, 2020). "In oral cancer cells, we found that treatment with naringin markedly reduced Bcl-2 and increased the expression of the anti-apoptotic genes BAD, BAX, and caspase-3." (PMID 39156270, 2024). "Resveratrol inhibits the function of thyroxine so that resveratrol supplementation enhances the expression of BAD and inhibits PD-1 to suppress oral cancer cells." (PMID 32486484, 2020). "In summary, this research emphasizes the potential of naringin as a cytotoxic and pro-apoptotic phytochemical that modulates the expression of Bcl-2, TGF-β, SMAD2, TNFα, NFκB, BAD, BAX, and caspase-3 genes, ultimately aiding the treatment of oral cancer." (PMID 39156270, 2024). "Overall, this study highlights the promising role of naringin as a pro-apoptotic and cytotoxic phytochemical regulating the gene expression of Bcl-2, TGF-β, SMAD2, TNFα, NFκB, BAD, BAX, and caspase-3, thereby treating oral cancer." (PMID 39156270, 2024). "The genes BAD, BAX, caspase-3, and Bcl-2 are thought to be markers specific to KB1 oral cancer cells." (PMID 39156270, 2024).
thyroid cancer (3 papers, 2010 to 2023). "Statistical analysis of the LFC profiles with the BRAF V600E-specific inhibitor dabrafenib differentiated BRAF V600E and non-BRAF V600E thyroid cancers, with six peptides (BAD_93- 105, CD27_212-224, MPIP1_172-184, PRKDC_2618-2630, and RB_242-254) showing p < 0.05." (PMID 37760447, 2023).
type 2 diabetes (3 papers, 2009 to 2023). "The BAD/GK complex was also disrupted in islets from humans with type 2 diabetes and showed an interesting similarity with islets from bIRKO mice." (PMID 19956695, 2009). "While BAD protein was expressed in both groups, p-BAD protein was virtually absent in β-cells in the diabetic group suggesting enhanced apoptosis in the pancreases from the type 2 diabetes cases who also exhibited blunted insulin signaling." (PMID 22140505, 2011).
glaucoma (2 papers, 2014 to 2022). Increased pressure in the eyeball due to obstruction of the outflow of aqueous humor. "Studies assume an involvement of BAD and active caspase-3 in glaucoma, which leads to the cellular protein cleavage and apoptosis." (PMID 24595072, 2014). "In addition, we also quantitatively analyzed both groups for the expression of apoptosis-related (BAD, BAX, BCL2L10, and XIAP) and autophagy-associated (HAX1 and Beclin-1) marker proteins, since both signaling cascades are supposed to be highly involved in the molecular pathogenesis of glaucoma." (PMID 36313990, 2022).
Huntington disease (2 papers, 2013 to 2021). Huntington disease (HD) is a rare neurodegenerative disorder of the central nervous system characterized by unwanted choreatic movements, behavioral and psychiatric disturbances and dementia. "CaN activation with consequent BAD dephosphorylation and Cytochrome C release are implicated in initiating neuronal cell death in several neurodegenerative diseases including AD, Parkinson’s disease (PD), and Huntington’s disease (HD)." (PMID 34722017, 2021). "The BAD, NEFH, NEFL and DERL1 genes are also involved in Huntington’s disease pathways." (PMID 23782433, 2013).
Insulin resistance (2 papers, 2017 to 2025). Increased resistance towards insulin, that is, diminished effectiveness of insulin in reducing blood glucose levels. "Common BAD and SERPINA6 variants were associated (p<0.05) with obesity and insulin resistance, respectively." (PMID 29126409, 2017). "It phosphorylates pro-apoptotic effectors (BAD, FOXO1) to enhance thyrocyte and orbital fibroblast survival, while mTORC1 hyperactivation accelerates metabolism, contributing to hypermetabolic phenotypes and insulin resistance." (PMID 41155084, 2025).
lymph node metastasis (2 papers, 2010 to 2024). "Herein, the phosphorylated to non-phosphorylated ratio of BAD, an effector of PI3K/AKT promoting cell survival, was observed to be correlated with worse clinicopathologic indicators of outcome, including higher grade, higher proliferative index and lymph node metastasis." (PMID 38200104, 2024).
myocardial infarction (2 papers, 2013 to 2024). Gross necrosis of the myocardium, as a result of interruption of the blood supply to the area, as in coronary thrombosis. "This action caused phosphorylation of the signaling molecules PI3K p85, Akt1, and BAD, thereby reducing caspase 3 activity, cell death, and myocardial infarction in association with improvement of myocardial function." (PMID 24067542, 2013).
rheumatoid arthritis (2 papers, 2020 to 2021). A chronic, systemic autoimmune disorder characterized by inflammation in the synovial membranes and articular surfaces. "BAD plays a key role in mitochondria-dependent apoptosis, and its inactivation contributes to the development of rheumatoid arthritis by conferring apoptosis resistance in synovial sub lining macrophages." (PMID 34702302, 2021). "BAD phosphorylation is increased in the synovial sublining macrophages of rheumatoid arthritis (RA) patients." (PMID 33270017, 2020).
skin cancer (2 papers, 2016 to 2021). "Further, it was found that several apoptotic genes including BAX, BAD were upregulated and survival genes such as Bcl-XL was down regulated in A375 skin cancer cell lines." (PMID 28330284, 2016). "Although BAD has not been previously implicated in skin cancers, loss or downregulation of other proapoptotic members of the BCL-2 family, i.e., BAX and PUMA, has been shown to promote the development of BCC, SCC, and cutaneous melanoma." (PMID 34900699, 2021).
Thrombocytopenia (2 papers, 2021 to 2025). A reduction in the number of circulating thrombocytes. "AKT1 facilitates the phosphorylation of BAD, a Bcl-2 family member, inhibiting its pro-apoptotic function and liberating the anti-apoptotic protein Bcl-XL, which safeguards B cells from apoptosis and may worsen thrombocytopenia." (PMID 41353393, 2025).
triple-negative breast carcinoma (2 papers, 2024). An invasive breast carcinoma which is negative for expression of estrogen receptor (ER), progesterone receptor (PR), and human epidermal growth factor receptor 2 (HER2). "We have shown previously that high integrin β3 levels in triple negative breast cancer contributed to chemoresistance by leading to the repression of BAD." (PMID 38786043, 2024).
acute lymphoid leukaemia (1 paper, 2022). "In Jurkat acute lymphoid leukaemia cells, there was a significant increase in the expression of BAD, BAX, and CYT c genes and proteins, as well as CASP-9 and CASP-3 genes when compared to the vehicle control (P ≤ 0.05)." (PMID 35614109, 2022).
alopecia (1 paper, 2014). Hair loss usually from the scalp. "BAD is an interesting causal candidate gene as it overlaps with a region on chromosome 11q13.1 known to be associated with multiple sclerosis, ulcerative colitis, IBD, alopecia, and Crohn's disease (ImmunoBase)." (PMID 25371288, 2014).
Arthritis (1 paper, 2020). Inflammation of a joint. "BAD differentially regulates the survival of various infiltrating immune cells in experimental arthritis." (PMID 33270017, 2020). "Thus, BAD is a key determinant for the development of experimental arthritis by regulating the survival of synovial sublining macrophages." (PMID 33270017, 2020). "Our findings put forward a model in which inactivation of BAD confers the apoptosis resistance on synovial sublining macrophages, thereby contributing to the development of arthritis, suggesting that BAD may be a potential therapeutic target for RA." (PMID 33270017, 2020). "Our finding identifies BAD as a crucial player in experimental arthritis pathogenesis." (PMID 33270017, 2020). "We also determined the pathological function of BAD in TNF-Tg mice, another murine model of experimental arthritis in which overexpression of human TNFα leads to inflammatory-erosive arthritis." (PMID 33270017, 2020). "Conversely, Bad3SA/3SA mice, in which BAD can no longer be inactivated by phosphorylation, are protected from collagen-induced arthritis." (PMID 33270017, 2020). "Thus, BAD is the convergent node for Akt and IKK signaling pathways to confer the resistance to apoptosis on synovial sublining macrophages, thereby contributing to the pathogenesis of arthritis." (PMID 33270017, 2020).
Autoimmunity (1 paper, 2017). The occurrence of an immune reaction against the organism's own cells or tissues. "BAD-LAMP therapeutic modulation could therefore represent a novel strategy for harnessing pDCs responses in different clinically relevant contexts such as autoimmunity or tumour development." (PMID 29030552, 2017).
breast disease (1 paper, 2010). "In the study of breast disease also found in the procession (normal - simple hyperplasia - atypical hyperplasia - carcinoma in situ - invasive breast cancer) the expression of BAD had a decreasing trend." (PMID 20691103, 2010).
Cerebral ischemia (1 paper, 2012). Restriction of arterial blood supply to the brain associated with insufficient oxygenation to support the metabolic requirements of the tissue. "Because phosphorylation of BAD has an anti-apoptotic effect, we investigated whether preconditioning with TWEAK decreases cerebral ischemia-induced apoptotic cell death." (PMID 22394384, 2012).
Chronic lymphocytic leukaemia (1 paper, 2016). "Chronic lymphocytic leukaemia cells were sensitive to BIM and BAD peptides but not to HRK or MS-1, consistent with their BCL-2-addiction." (PMID 26954718, 2016).
cognitive decline (1 paper, 2024). "Furthermore, additional studies on the link between human brain aging or aging-related cognitive decline and changes in the expression of ASPHD2, BAD, CRTAP, IPW, and ZNF106 which remain elusive, may also be advantageous." (PMID 38428408, 2024).
cognitive deficits (1 paper, 2022). "On the other hand, increased β-cleavage of Swedish APP in the ISVAID may directly prompt L-LTP and cognitive deficits via potentiation of the BAD-Glu pathway." (PMID 36438008, 2022).
dyslipidemia (1 paper, 2017). "Common variants in OGFOD3 and APOB as well as rare and common BAD variants were significantly (p<0.05) associated with dyslipidemia." (PMID 29126409, 2017). "The common variant rs2286615 in the BAD gene was associated with extreme phenotype and obesity, whereas interactions between rare and common variants were linked to extreme phenotype and dyslipidemia." (PMID 29126409, 2017).
E. coli infection (1 paper, 2019). "Matching the previous results, E. coli infection did only lead to BAD phosphorylation in CBMO but not in PBMO." (PMID 32082070, 2019).
esophageal cancer (1 paper, 2016). A primary or metastatic malignant neoplasm involving the esophagus. "Similarly, OCT1 was discovered to be directly regulated by STAT3 to reduce the expression of caspase 9, BAX, and BAD via ERK and AKT activation to boost proliferation and inhibit apoptosis in esophageal cancer cells." (PMID 26433389, 2016).
fibrosis (1 paper, 2021). the formation of excess fibrous connective tissue in an organ or tissue in a reparative or reactive process. "The same results further presented that BAD translocated to mitochondria in lung tissues of bleomycin-induced fibrosis, which was dramatically suppressed in lentivirus-mediated TSSK4-deficient model mice." (PMID 34645797, 2021).
gastric adenocarcinoma (1 paper, 2016). "ERK could phosphorylate BAD at Ser-112 via p90RSK and promotes cell proliferation of human gastric adenocarcinoma cells, similar to its classical regulatory mechanism." (PMID 26811493, 2016). "In addition, we demonstrated that Akt could phosphorylate its substrates, including BAD at Ser-136 and S6 at Ser235/236, to promote cell proliferation and protein synthesis of human gastric adenocarcinoma cells, as described in the conventional regulatory mechanism of Akt." (PMID 26811493, 2016).
gastric tumor (1 paper, 2016). "Collectively, these results indicated that hsa-miR-376c-3p expression regulated the gastric tumor cell growth in vitro through BAD/BCL-2 pathway." (PMID 27965982, 2016).
glomerulosclerosis (1 paper, 2020). A hardening of the kidney glomerulus caused by scarring of the blood vessels. "In conclusion, MES + HS ameliorated urinary protein leakage and glomerulosclerosis in a murine model of ADR nephropathy via regulation of Akt-BAD axis." (PMID 33128027, 2020).
Glucose intolerance (1 paper, 2009). Glucose intolerance (GI) can be defined as dysglycemia that comprises both prediabetes and diabetes. "Similar to effects observed in BAD-deficient hepatocytes, decreased BADS protein in the βIRKO cells likely contributes to mitochondrial dysfunction and β-cell dysfunction, which may contribute to the glucose intolerance in both of these mutants." (PMID 19956695, 2009).
Hepatic fibrosis (1 paper, 2023). The presence of excessive fibrous connective tissue in the liver. "Recent studies have found that metformin can improve liver function and hepatic fibrosis induced by NASH by upregulating BIM, BAD and PUMA and downregulating Bcl-2 and Bcl-xL to induce apoptosis in HSCs, which provides a new approach for the management of hepatic fibrosis." (PMID 38086792, 2023).
hepatoblastoma (1 paper, 2021). Hepatoblastoma (HB) is a malignant hepatic tumor and is the most common pediatric liver cancer. "We previously demonstrated that PIM3 phosphorylated BAD in hepatoblastoma impeding apoptosis and promoting tumorigenesis." (PMID 33727604, 2021). "Kinome profiling revealed that phosphorylation of BAD was increased in cisplatin-resistant hepatoblastoma tumors compared to their naïve counterparts." (PMID 33727604, 2021).
HIV-1 infection (1 paper, 2022). The type species of lentivirus and the etiologic agent of acquired immunodeficiency syndrome (AIDS). "Here, expression of the pro-apoptotic protein BAD increased after HIV-1 infection and was reduced in the presence of cART." (PMID 35132117, 2022). "Additionally, we also observed increased expression of both cleaved PARP-1, Caspase-3, and BAD in response to HIV-1 infection." (PMID 35132117, 2022).